RETN (resistin)
Diseases named in the same sentence as RETN in open-access papers (continued):
Sharing a sentence is not in itself a finding about the gene and the disease.
breast cancer (continued). "Furthermore, resistin has been reported to be elevated in obese individuals and among breast cancer patients (not adjusted for BMI), although the results have been conflicting." (PMID 30524378, 2018). "In addition, resistin expression levels were higher in breast cancer tissues than in adjacent non-malignant breast tissue." (PMID 27314854, 2016). "However, no reports exist as to any association between resistin and EGFR in breast cancer." (PMID 33313320, 2020). "Elevated levels of resistin and epidermal growth factor receptor (EGFR) facilitate the development of breast cancer, although there are no reports of any correlation between these proteins." (PMID 33313320, 2020). "In this study, both resistin and EGFR impacted adversely upon survival in breast cancer, but neither protein alone had a significant impact." (PMID 33313320, 2020). "The data show that all the breast cancer cell lines express varying levels of IL-6, CAP1 and IL-6R, whereas no expression of resistin is observed either at the protein or transcript level in any of the cell lines (data not shown)." (PMID 25868978, 2015). "We assessed the mRNA expression of resistin, tumor necrosis factor-alpha (TNF-α), interleukins 6 and 8 (IL-6, and IL-8), and estrogen receptor alpha (ER-α) in peripheral blood mononuclear cells (PBMCs) of women with and without breast cancer." (PMID 33517609, 2021). "Together, the TAZ/Resistin/TLR4 axis may serve as a link between adipocyte and nonautonomous breast cancer progression, and Resistin might be a therapeutic target for clinical breast cancer treatment." (PMID 33318171, 2020).
Hypertension (73 papers, 2009 to 2026). The presence of chronic increased pressure in the systemic arterial system. "Visfatin rises with hypoxia and is seen in hypertension, while resistin is associated with insulin resistance and hypertension in diabetics." (PMID 41155389, 2025). "High levels of resistin are associated with metabolic diseases and their complications, including hypertension." (PMID 38164476, 2024). "The K. Dimitriadis study revealed an independent association of resistin with eGFR in young people with arterial hypertension, which suggests the involvement of resistin in the progression of kidney damage." (PMID 37623488, 2023). "Recently, studies have shown the association between circulating resistin levels and hypertension phenotype." (PMID 35565757, 2022). "The relationship between resistin, its polymorphism, and markers of endothelial dysfunction in the course of hypertension requires further studies." (PMID 35565757, 2022). "Multivariable analysis suggested hypertension-resistin-HbA1c interactions associated with SAT’s larger adipocytes; whereas potential insulin-adiponectin associations were observed for VAT’s larger adipocytes." (PMID 33469087, 2021). "In this context, the potential role of resistin as a risk factor for hypertension has also been confirmed in a recent meta-analysis." (PMID 33192583, 2020). "A positive association between resistin serum levels and hypertension was identified in this meta-analysis (SMD = 0.85, 95% CI: 0.15–1.54, P = 0.02)." (PMID 28525369, 2017). "The mechanism underlying the association between the resistin and hypertension still remains to be elucidated." (PMID 28525369, 2017). "This has not been investigated, however, several clinical studies have shown that plasma resistin levels are associated with either the presence or the development of high blood pressure in humans." (PMID 26617526, 2015). "Accumulating evidence suggests that resistin influences blood pressure regulation; its levels are higher in patients with HTN compared to normotensive individuals, indicating that resistin may be a risk factor for the development of hypertension." (PMID 40283140, 2025). "Collectively, these findings suggest that resistin may represent a risk factor for the development of hypertension and could potentially be used as a biomarker for this condition." (PMID 40283140, 2025). "In patients with CAD, hypertension, and type 2 DM, resistin is negatively associated with eGFR." (PMID 37763771, 2023). "Creatinine and hypertension showed the strongest association with resistin levels." (PMID 34496965, 2021). "Moreover, neurotransmitters that can influence the activity of PVN-RVLM neurons can be used as therapeutic targets in cardiovascular diseases such as HF and hypertension, which are associated with high levels of resistin." (PMID 32440321, 2020). "Adiponectin decreases the production of angiotensin II and thereby promotes high blood pressure while resistin is associated with increases in TNF-α receptor-2 and IL-6, leading to increased level of endothelin which constricts blood vessels and raises blood pressure." (PMID 33014422, 2020). "As circulating resistin levels are associated with inflammatory markers, it appears that by inducing and propagating inflammatory processes especially in heart and blood vessels, resistin leads to the pathogenesis of hypertension and coronary artery disease." (PMID 31258568, 2019). "Based on our results, we conclude that serum resistin level in hypertensive patients is higher than normotensive controls, indicating resistin might be a risk factor for hypertension." (PMID 28525369, 2017). "Therefore, in this study we carried out a systematic review to synthesize and analyze the published data on the association of resistin with the risk of hypertension." (PMID 28525369, 2017). "One of these genes (Retn, resistin) is known as associated with hypertension." (PMID 28105926, 2016).
Hypertension (continued). "Besides its BP-lowering effect, we found that Eplerenone also significantly decreased the plasma concentrations of resistin and IL-6, both of which have been associated with inflammation and hypertension in obesity." (PMID 27032687, 2016). "The mechanism underlying the association between resistin and hypertension remains unclear." (PMID 35565757, 2022). "So this study is designed to determine the possible inflammatory role of resistin by observing its association with other documented inflammatory biomarkers such as TLC & CRP in cases of variable degrees of cardiovascular disease i.e. hypertension, angina pectoris and myocardial infarction." (PMID 31258568, 2019). "This could also explain the association between the resistin and hypertension." (PMID 28525369, 2017). "Thomopoulos and colleagues reported that increased resistin and decreased adiponectin plasma levels are asscciated with sustained and masked hypertension, and resistin is associated 2.5 times more frequently with sustained hypertension than with masked hypertension." (PMID 28525369, 2017). "The analysis revealed that sdLDL, resistin, and hypertension were significant independent predictors." (PMID 41315571, 2025). "In humans, TLR4 and resistin appear to play a significant role in the development of hypertension in T2D." (PMID 40283140, 2025). "Smokers and participants with hypertension showed higher sdLDL (p = 0.03, p = 0.0001) and resistin levels (p = 0.03, p < 0.0001)." (PMID 41315571, 2025). "The current study clarifies that the smoking was not a significant factor in our multivariate logistic regression analysis, but sdLDL, resistin, and hypertension were found to be strong, independent predictors of a higher BMI category." (PMID 41315571, 2025). "Hypertensive obese participants exhibit significantly elevated srum resistin level, suggesting a possible connection between resistin and hypertension pathophysiology of hypertension." (PMID 41315571, 2025). "Another proposed mechanism is that resistin increases the expression and release of endothelin-1 (ET-1) and downregulates endothelial nitric oxide synthase in human cells, resulting in hypertension." (PMID 40283140, 2025). "In individuals with both T2D and hypertension, resistin levels are even higher and show a positive correlation with mean arterial pressure values." (PMID 40283140, 2025). "This study aimed to estimate the relationship between resistin (−420G/C) single nucleotide variant (SNV) and markers associated with endothelial dysfunction in hypertension." (PMID 35565757, 2022). "The serum concentration of resistin was similar in the studied population when evaluated according to hypertension phenotype or salty taste preference, which was compared among genotypes and GG + GC vs. CC individuals." (PMID 35565757, 2022). "This study demonstrates that non-dialysis CKD stage 3 to 5 patients with low ABI tended to be older aged, lower eGFR, and had DM, hypertension, used tobacco more and had markedly elevated serum resistin levels." (PMID 34886472, 2021). "Several clinical studies have reported correlations between plasma resistin levels and high blood pressure." (PMID 33679451, 2021). "Serum resistin levels along with CRP and TLC are significantly raised in patients of hypertension and coronary artery disease while resistin levels revealed significantly positive correlation with TLC in hypertensive patients of myocardial infarction." (PMID 31258568, 2019). "The present study supports the inflammatory role of resistin in patients of hypertension and coronary artery disease." (PMID 31258568, 2019). "Our objective was to compare the levels of serum resistin, C-reactive protein and total leucocyte count in subjects of hypertension and coronary artery disease; and to observe the correlation of serum resistin with CRP and TLC in the study participants." (PMID 31258568, 2019).
Hypertension (continued). "Our results demonstrated progressive increase in serum resistin levels in patients of hypertension and coronary artery disease as compared to normal subjects." (PMID 31258568, 2019). "Resistin levels are elevated in hypertension, and, thus, the parallel decrease of systolic blood pressure and resistin in the present study is in alignment with this." (PMID 29599686, 2018). "Later studies pointed to a role of resistin in the pathogenesis of hypertension possibly via inflammatory processes." (PMID 28611687, 2017). "All articles were case-control studies reporting the relationship between serum resistin levels and hypertension in European, Asian and Hispanic populations." (PMID 28525369, 2017). "Taken together, the present study revealed higher serum resistin levels in hypertensive patients compared to healthy controls, indicating that elevated serum resistin levels correlated with hypertension development." (PMID 28525369, 2017). "The results of initial efforts were conflicting, with some, but not all studies identifying a significant correlation between serum resistin level and hypertension incidence." (PMID 28525369, 2017). "Ten of those studies reported higher resistin level in the hypertension patients, and seven of them were statistically significant." (PMID 28525369, 2017). "Subgroup analysis showed that the correlation between the resistin and hypertension is more consistently reported in Asian and Hispanic populations." (PMID 28525369, 2017). "In our analysis, fourteen case-control studies investigating the correlation between serum resistin concentration and hypertension were included." (PMID 28525369, 2017). "Many studies have investigated the correlation between circulating resistin levels and hypertension." (PMID 28525369, 2017). "Taken together, these data demonstrate that the action of resistin on hypertension and IR is mediated by TLR4." (PMID 26917360, 2016). "Pre-treatment of mice with the ACE inhibitor perindopril abolished resistin-induced hypertension and IR, suggesting that the action of resistin is inhibited when the RAS is blocked." (PMID 26917360, 2016). "Our data showed that resistin induces both IR and hypertension in mice and these effects are TLR4-dependent." (PMID 26917360, 2016). "This also fits to the finding in our mouse model on the importance of resistin linking IR and hypertension." (PMID 26917360, 2016). "A positive correlation between plasma resistin levels and hypertension, measured using 24 h ambulatory blood pressure monitoring, has been observed." (PMID 26617526, 2015). "Increased plasma resistin levels has also been observed in a young healthy population with a family history for essential hypertension." (PMID 26617526, 2015). "In our study, despite the fact that resistin does not lead in terms of predictive capabilities in relation to the risk of hypertension, we noted its significant effect on systolic blood pressure." (PMID 41596212, 2026). "Among them, resistin appears to be an independent predictor of hypertension and may represent a potential biomarker for cardiovascular risk assessment." (PMID 42037998, 2026). "The role of adiponectin and resistin in the development of hypertension remains unclear and requires broader studies." (PMID 41596212, 2026). "Level of resistin was compared with different parameters and clinical outcome of study participants and observed to have statistically significant difference with smoking and hypertension parameters." (PMID 41315571, 2025). "Its ability to modulate neurohormonal pathways, including sympathetic activation and interactions with the endocannabinoid system, further integrates resistin into a complex network that exacerbates hypertension, arrhythmogenesis, and adverse cardiac remodeling." (PMID 41347124, 2025).
Hypertension (continued). "Its ability to modulate neurohormonal pathways, including enhancing sympathetic outflow and interacting with the endocannabinoid system, further integrates resistin into a complex network that exacerbates hypertension, arrhythmogenesis, and adverse cardiac remodeling." (PMID 41347124, 2025). "Overall, higher resistin concentrations were significantly associated with smoking and hypertension, but not with gender, age, or physical activity." (PMID 41315571, 2025). "Additionally, resistin exacerbates sympathetic nervous system activation and modulates the renin-angiotensin-aldosterone system, promoting hypertension and afterload elevation—critical drivers of HFpEF progression." (PMID 41347124, 2025). "Likewise, participants with hypertension exhibited markedly elevated resistin concentrations (1136 ± 364.6 pg/mL) relative to normotensive individuals (921.5 ± 372.2 pg/mL, p < 0.0001)." (PMID 41315571, 2025). "Finally, a meta-analysis published in 2017 found that the correlation between serum resistin and hypertension differs across populations, being more consistent in Hispanic and Asian populations." (PMID 40283140, 2025). "With adjustments for age, sex, regular smoking, regular alcohol intake and treatment for hypertension, BMI (partial r = 0.03, p = 0.40) and WC (partial r = 0.02, p = 0.59) were not independently associated with resistin concentrations." (PMID 32000666, 2020). "A positive correlation between serum resistin levels and hypertension was shown in humans." (PMID 33192583, 2020). "The values of serum resistin, C- reactive protein and total leukocyte count were found significantly raised in patients of hypertension, angina pectoris and myocardial infarction with hypertension as compared to normal participants (p<0.001 for all)." (PMID 31258568, 2019). "Serum levels of resistin, C-reactive protein and total leucocyte count are significantly raised with increasing inflammatory pathogenesis of the cardiovascular disease in patients of hypertension and coronary artery disease as compared to normal subjects." (PMID 31258568, 2019). "Further, a recent study suggests resistin contribute to hypertension via TLR4 signalling." (PMID 31053755, 2019). "In addition, the studies with larger cohort size showed more significant correlation between resistin and hypertension patients than the small sized studies." (PMID 28525369, 2017). "It has been reported that resistin could induces hypertension in wild type (WT) mice by activating the renin-angiotensin system through up-regulation of Agt expression in the liver." (PMID 28525369, 2017). "It still remains to be shown whether high resistin level contributes to hypertension development, or high blood pressure induces resistin expression in human population by other types of study design." (PMID 28525369, 2017). "Recent studies have shown that adipokines, such as adiponectin, leptin and resistin might involve in the development of hypertension." (PMID 28525369, 2017). "In order to consider other factors that may affect the link between serum resistin level and hypertension, we performed a stratified analysis based on ethnicity and sample size." (PMID 28525369, 2017). "Plasma resistin levels were reduced from baseline with barnidipine + losartan treatment but were not reduced with telmisartan + hydrochlorothiazide treatment in patients with hypertension and type 2 DM." (PMID 28806778, 2017). "Thus, the vast majority of studies have shown a correlation between plasma resistin levels and hypertension." (PMID 26617526, 2015). "The relationship among resistin, hypertension and endothelial function is even more complex." (PMID 22938533, 2012). "Our study, for the first time, to the best of our best knowledge, demonstrated that resistin SNV (−420G/C) is related to hypertension and may interplay with markers of endothelial dysfunction, including serum UA concentration, SI value, and salt taste preference in hypertensive patients." (PMID 35565757, 2022).